CD38 (CD38 molecule)
Diseases named in the same sentence as CD38 in open-access papers (continued):
Sharing a sentence is not in itself a finding about the gene and the disease.
multiple myeloma (continued). "This difference was significant for CD38-expression (GEP) in asymptomatic vs. symptomatic myeloma (n = 34, p = 0.01; Figures 2D1–D3) and symptomatic vs. relapsed myeloma in flow cytometry (n = 52, p = 0.001), however, the absolute difference was small (Figures 2E1,E2)." (PMID 30079070, 2018). "Treatment with 10 or 20 mg/ml Elo resulted in full saturation of more than 80% of SLAMF7 binding sites on CD38+ myeloma cells and consistently achieved Elo serum concentration of more than 70 ug/ml in patients, with peak concentrations of up to 1 mg/ml in serum." (PMID 30455698, 2018). "Daratumumab, an anti-CD38 monoclonal antibody, has been approved as a therapy for multiple myeloma." (PMID 30631755, 2018). "Over several decades, monoclonal antibodies to CD38 had been developed for use against hematological malignancies without success until the identification of daratumumab, a monoclonal anti-CD38 approved for myeloma in late 2015." (PMID 30356940, 2018). "In addition, the anti-CD38 monoclonal antibodies daratumumab and isatuximab show therapeutic benefits in multiple myeloma and are proposed as potential therapies for other conditions." (PMID 30042766, 2018). "However, this does not seem to be the cause of failure of the treatment because many patients continue to maintain a response despite the low levels of CD38 expression by myeloma cells." (PMID 29915586, 2018). "Preclinical studies have also shown that panobinostat may increase the expression of CD38 by myeloma cells and improve the response to daratumumab in vitro." (PMID 29915586, 2018). "Anti-CD38 monoclonal antibodies such as daratumumab are important components of myeloma treatment." (PMID 29806594, 2018). "We therefore determined CD38 expression on myeloma cells upon culture with TMEFs." (PMID 29500635, 2018). "The NAD+-metabolizing ectoenzyme CD38 is an established therapeutic target in multiple myeloma." (PMID 30459772, 2018). "In myeloma cells, CD38 is overexpressed ectopically, and it is unclear whether extracellular NAD is involved in tumor progression." (PMID 30631755, 2018). "Another possible limitation is represented by the variable expression of CD38 on myeloma cells." (PMID 30546360, 2018). "Moreover, the CD38-specific biparatopic heavy chain antibodies described here represent potential new powerful therapeutics for treatment of multiple myeloma." (PMID 30524421, 2018). "Future studies are needed to assess whether this enhancing effect by a CD38-specific hcAb also renders myeloma cells of patients that have become refractory to daratumumab susceptible to CDC." (PMID 30524421, 2018). "In this manuscript, we address three of these: first, upfront CD38 target-expression in AL-amyloidosis, monoclonal gammopathy of unknown significance (MGUS), asymptomatic, symptomatic, and relapsed multiple myeloma." (PMID 30079070, 2018). "By contrast, high CD38-expression is prognostically adverse in AL-amyloidosis." (PMID 30079070, 2018). "The cell surface ecto-enzyme CD38 is a promising target antigen for the treatment of hematological malignancies, as illustrated by the recent approval of daratumumab for the treatment of multiple myeloma." (PMID 29084989, 2017). "A role of CD38 in the pathophysiology is postulated due to its high expression on a variety of hematological malignancies including multiple myeloma, B- and T- acute lymphoblastic leukemia (ALL), Non-Hodgkin lymphoma (NHL), Acute myeloid leukemia (AML) and Chronic Lymphocytic Leukemia (CLL)." (PMID 31548533, 2017). "In preclinical studies, it was found that daratumumab (formerly named HumaxCD38) kills CD38-expressing lymphoma and myeloma cells by various mechanisms including CDC, ADCC, ADCP, and induction of apoptosis after Fcγ receptor-mediated crosslinking with anti-human IgG1 secondary antibody." (PMID 31548533, 2017). "Importantly, BCMA has a more specific expression pattern when compared with the other multiple myeloma antigens CD38 and SLAMF7." (PMID 31548533, 2017).
multiple myeloma (continued). "The CD38 target is gaining attention from recent approval of Daratumumab (Darzalex; Janssen Biotech, Horsham, PA), the first clinically approved antibody specific to human CD38 for the treatment of multiple myeloma." (PMID 27434591, 2016). "Cost is a major concern in myeloma therapy, and the availability of two monoclonal CD38 antibodies on the market may help with affordability." (PMID 27471867, 2016). "The continued expression of the target throughout treatment also would need to be confirmed, necessitating repeat immunophenotyping and alternative myeloma signature surface markers would be required where important original markers such as CD38 and CD138 are targeted." (PMID 27775669, 2016). "Furthermore, CD38 expression is maintained in spite of the genomic differences marking myeloma cells." (PMID 26393653, 2015). "Binding of 213Bi-anti-CD38-MAb to the myeloma cell lines RPMI8226, OPM2, and ARH77 was different." (PMID 25576914, 2015). "CD38 has played a crucial role in the story of human multiple myeloma." (PMID 26393653, 2015). "Because of its quantitative expression, CD38 might represent a ruler of NAD+ levels inside the niche where the myeloma grows." (PMID 26393653, 2015). "Moreover, information gathered by pooling experimental data with empirical observations indicates that the hypoxic conditions present in the myeloma niche apparently favor the CD38/CD203a(PC-1)/CD73/TRAP pathway at the expense of the canonical axis." (PMID 26393653, 2015). "DARA is a human anti-human CD38 mAb in phase III clinical trials in patients with multiple myeloma." (PMID 26393653, 2015). "The induction of MV may be relevant for in vivo myeloma therapy: MV are extrusions of the cell membrane and bear on their surface a set of molecules clustered in lipid microdomains, where the presence of CD38 has been confirmed." (PMID 26393653, 2015). "Building on these encouraging results with α-emitters in treatment of hematological malignancies and due to the high expression of CD38 in malignant plasma cells we evaluated therapeutic efficacy of 213Bi-anti-CD38 radioimmunoconjugates in multiple myeloma both in vitro and in vivo." (PMID 25576914, 2015). "Two lines of evidence indicate that CD38 is not a mere diagnostic marker but is also a key element in the pathogenetic events underlying myeloma development." (PMID 24489445, 2013). "Myeloma is a tumor growing in closed system where the enzymatic activity of CD38 may be complemented by those exerted by PC-1/CD203a and CD73." (PMID 24489445, 2013). "CD138 gating identifies a much more homogeneous population of myeloma cells than does CD38 gating." (PMID 24744630, 2012). "CD38 monoclonal antibody (Isatuximab;) and inhibitors are currently being used for treating patients with multiple myeloma and other cancers and have been proposed for the treatment of neurodegeneration, based on the prediction that increasing NAD+ levels could be neuroprotective." (PMID 41400119, 2026). "In summary, well-selected MM patients may show rewarding response to daratumumab/CD38-antibody-retreatment, the more with different anti-myeloma combination drugs, initial good response and CD38-antibody treatment pauses, proving this retreatment as feasible, effective and non-toxic." (PMID 39311957, 2025). "Moreover, the monoclonal anti-CD38 antibody daratumumab, currently approved for multiple myeloma, has demonstrated renal function improvement in patients with myeloma-related kidney injury, although its application in diabetic nephropathy remains experimental due to potential immune effects." (PMID 41470091, 2025). "Moreover, deletion of the CD38 gene prevents fratricide induced by daratumumab (anti-CD38) binding to CD38 on NK cell membranes, leading to a 50% enhancement in anti-tumor activity during combination therapy in multiple myeloma xenograft models (n = 12)." (PMID 41488873, 2025).
multiple myeloma (continued). "In comparison, incorporation of daratumumab, an anti-CD38 monoclonal antibody, represents a more promising therapeutic approach in combination with lenalidomide and dexamethasone, given its balance of tolerability and efficacy in both patients with multiple myeloma and POEMS." (PMID 41281020, 2025). "For example, it is important to determine whether there is a preferential killing of CD38+ NK-cells over myeloma cells during bouts of exercise, and to assess this impact of exercise in a larger, more diverse cohort of patients before recommendations of exercise timing during therapy can be made." (PMID 39411424, 2024). "To date, the FDA-approved anti-CD38 monoclonal antibodies (mAbs), daratumumab (Darzalex, Janssen) and isatuximab (Sarclisa, Sanofi), have demonstrated encouraging anti-MM activity with manageable safety profiles for both relapsed/refractory multiple myeloma (RRMM) and newly diagnosed MM." (PMID 38765013, 2024). "Isatuximab achieves myeloma cell killing via multiple mechanisms, including antibody-directed cellular cytotoxicity, antibody-dependent cellular phagocytosis, complement-dependent cytotoxicity, direct apoptosis, direct activation of natural killer cells, and inhibition of CD38 ectoenzyme activity." (PMID 39609425, 2024). "In addition, the remaining myeloma cells during Dara treatment have low CD38 expression." (PMID 38410372, 2024). "Furthermore, anti-myeloma regimens including combinations of proteasome inhibitors (bortezomib, ixazomib, carfilzomib) with either an anti-CD38 monoclonal antibody (daratumumab) or an immunomodulatory drug (lenalidomide, thalidomide) seem to improve indices of bone metabolism." (PMID 39518598, 2024). "Finally, we assessed whether the increase in CD38 antigen expression promoted by tinostamustine was able to improve the binding of daratumumab to myeloma cells." (PMID 38731936, 2024). "Since EZH2 inhibition is already approved for the treatment of B cell lymphoma, we believe our study may provide new therapeutic avenues to investigate the efficacy of EZH2 inhibition as a strategy to re-sensitize myeloma cells to anti-CD38 MoAbs and overcome resistance." (PMID 37532787, 2023). "Notably, a more advanced patient population was enrolled in this trial since patients were required to have suffered disease progression after three or more LOT, and their myeloma had to be refractory to both IMiDs and PIs, and either refractory or intolerant (or both) to an anti-CD38 antibody." (PMID 37111346, 2023). "Moreover, Daratumumab, an anti-CD38 monoclonal antibody delivered in multiple myeloma patients to eradicate plasma cells, may also contribute to the elimination of CD38-expressing MDSCs." (PMID 36401744, 2023). "The development of resistance to therapy remains the main barrier to cure myeloma, and most patients develop disease that is refractory to treatments, including proteasome inhibitors (PIs), immunomodulatory drugs (IMiDs) and monoclonal antibodies targeting CD38." (PMID 37936678, 2023). "In contrast, other studies postulated that myeloma stem cells are characterized by a CD38+ CD138+ CD19- CD45- immunophenotype suggesting that stem cell related markers might undergo dynamic changes or differ between MM patients and the experimental model systems." (PMID 37744361, 2023). "Meanwhile, anti-CD38 MoAb could contribute to myeloma cell death by not only binding to myeloma cells but also several immune cells, leading to reduced abundance of regulatory T cells (Tregs) and activation of cytotoxic T lymphocytes and natural killer (NK) cells." (PMID 37173885, 2023). "The extensive utilization of anti-CD38 monoclonal antibodies has led to favorable outcomes, including improved hematologic CR rates, more organ responses (particularly cardiac responses) in AL amyloidosis patients, and even enhanced one-year OS for stage IIIB patients." (PMID 38068514, 2023).
multiple myeloma (continued). "With the introduction of the anti-CD38 monoclonal antibody (daratumumab)-based combination regimen in the front-line setting, significant improvements in hematologic complete response (CR), organ responses, and potentially enhanced OS have been realized for AL amyloidosis patients." (PMID 38068514, 2023). "Additionally, as these NK cells are intended to be combined with an anti-CD38 antibody (Daratumumab) to target multiple myeloma, CD38 was deleted from the iPSCs to produce CD38-knockout (KO) iPSC-NK cells that also contain the engineered CD16 and IL15 molecules." (PMID 35185932, 2022). "However, the density and high levels of CD38 on PC relative to other cells identified this protein as an optimal target for anti-myeloma therapy, and indeed, anti-CD38 antibodies have revolutionized the anti-myeloma treatment." (PMID 35407416, 2022). "CD38 may be also a good target for CAR-T in refractory or relapsed multiple myeloma (RRMM)." (PMID 36077708, 2022). "Similarly, an investigation into the potential therapeutic effects of CD38-specific nanobody-based CAR (Nb-CARs) revealed that Nb-CAR-NK-92 cells might induce cytotoxicity against primary patient-derived CD38-expressing myeloma cells." (PMID 36153626, 2022). "In addition, the combination of BI-D1870 and ipatasertib showed significantly more powerful growth suppression compared to the effect by either ipatasertib or BI-D1870 alone, not only in HMCLs, but also in primary myeloma cells from a patient who acquired resistance to PI, IMiDs, and anti-CD38 MoAb." (PMID 35328342, 2022). "Most publications on CD38 utilize CD38-targeted tracers for imaging of multiple myeloma, but CD38 was recently identified as a possible target for checkpoint inhibition, therefore CD38-targeted tracers might also find application in immunotherapy monitoring, but were not included in this review." (PMID 35630835, 2022). "In particular, active treatment with anti-CD38 monoclonal antibodies or anti-BCMA bispecific antibodies was associated with decreased CD4+ T cell responses, while patients treated with anti-BCMA CAR T cells mounted similar CD4+ T cell responses compared to myeloma patients receiving other therapies." (PMID 35214642, 2022). "New treatment strategies and modalities are necessary to treat myeloma in relapse, particularly in cases of triple-refractory status defined by disease progression during or shortly after treatment with immunomodulatory agents, proteasome inhibitors, and anti-CD38 monoclonal antibody therapy." (PMID 35877215, 2022). "How anti-CD38 antibodies should be sequenced and whether additional anti-myeloma activity can be achieved from an anti-CD38 antibody in RRMM patients already exposed to anti-CD38 therapy are important clinical questions currently being addressed by investigators." (PMID 35943588, 2022). "The expression of CD38 could be also relevant as a potential therapeutic target (anti-CD38 antibodies daratumumab and isatuximab approved in the US, Europe, and Italy for the treatment of multiple myeloma)." (PMID 35251370, 2022). "Resistance to DARA may result from upregulation of the complement inhibitory proteins CD55 and CD59, downregulation of the DARA target CD38 on myeloma cells or altered expression of the checkpoint inhibitor ligand programmed death ligand-1 (PD-L1) or other mechanisms." (PMID 36359760, 2022). "Anti-CD38 antibodies mediate anti-myeloma activity through multiple mechanisms of action both in patients with RRMM and with newly diagnosed MM, although immunomodulatory effects may be greater in earlier disease settings in which the immune system has not been affected by prior treatments." (PMID 35943588, 2022). "In addition to myeloma cells, CD38 also expresses on the RBC membrane." (PMID 34752645, 2021). "Blocking both CD38 and PD-L1 could thus revert BM MSCs effects and prevent myeloma growth." (PMID 33418913, 2021).
multiple myeloma (continued). "Nevertheless, the best-known field of application of CD38 as a pharmacological target is arguably represented by hematological malignancies: different anti-CD38 monoclonal antibodies have been developed and are currently in use or in clinical trials, especially in multiple myeloma." (PMID 34835990, 2021). "However, due to the long half-life of CD38-antibodies, intermittent pausing of these therapeutics for several months as would be needed to fully clear the antibody seems impractical and would likely endanger successful myeloma treatment." (PMID 34359701, 2021). "Here, nanobody-based CD38-specific hcAbs are able to induce antibody-dependent cellular cytotoxicity in tumor cancer cell lines and inhibit tumor growth in a mouse xenograft model, warranting further clinical development as therapeutics for multiple myeloma and other hematological malignancies." (PMID 34131806, 2021). "Therefore, we attempted additional experiments to confirm whether venetoclax could enhance CDC by daratumumab using two CD38-positive myeloma cell lines (KMS12PE and KMS27), which were used in this study and had revealed daratumumab mediated ADCC." (PMID 34639102, 2021). "Moreover, it could be hypothesized that CD38 expression levels are predictive for response to daratumumab in prostate cancer patients, as previously reported in refractory multiple myeloma." (PMID 34638258, 2021). "Thus, BOR might enhance the anti-myeloma effect of anti-CD38 MoAb such as daratumumab (DARA) via the inhibition of adhesion between myeloma cells and BMSCs." (PMID 33435539, 2021). "However, CD38 is expressed at high levels on malignant myeloma cells." (PMID 34141513, 2021). "Daratumumab targeting of CD38+ NK cells may play a pivotal role in initiating a Th1-mediated immune response, which can be an essential component in mounting a powerful anti-CD38 immune response against myeloma cells." (PMID 33806310, 2021). "Thus, the efficacy of anti-CD38 MoAb could be related to the anti-CD38 free interval, and the immunophenotypic characteristics of residual myeloma cells could predict resistance to anti-CD38 MoAbs." (PMID 34638353, 2021). "More recently, CD38 was shown to be involved in MM cell proliferation and survival by facilitating protective myeloma cell–stroma cell interactions, enabling mitochondrial transfer between bone marrow stromal cells (BMSCs) and myeloma cells by forming tunneling nanotubes (TNTs)." (PMID 32331242, 2020). "Interestingly, adenosine generated in the bone marrow niche via CD38-mediated pathway is correlated with progression of myeloma; thus, this mechanism of isatuximab might contribute to antitumor immunity in this environment." (PMID 32922390, 2020). "Selective elimination of myeloma cells with high CD38 expression and survival of myeloma cells with low CD38 expression could potentially explain a reduced expression of CD38, but since the phenomenon is also observed in non-responding patients, this explanation may be less likely." (PMID 32041300, 2020). "Furthermore, the more frequent combination use of anti-CD38 mAbs, in particular with IMiDs, is likely to trigger a powerful response of all the immune competent apparatus against Myeloma cells with unexpected results, thus paving the way for a putative cure of the disease." (PMID 32245149, 2020). "Furthermore, increased risk of infection was also observed in a study exploring the effects of daratumumab in patients with systemic light-chain amyloidosis and in clinical trials using isatuximab, a separate anti-CD38 monoclonal antibody, for multiple myeloma." (PMID 31963337, 2020). "In order to speculate on the potential effect of anti-CD38 antibodies in AL amyloidosis, the mechanisms through which DARA (the most analyzed anti-CD38 agent) exerts its cytotoxic role on effector cells in MM (that is mainly mediated by anFcR-dependent mechanism) should be mentioned." (PMID 32531894, 2020).